CLU (clusterin)
Diseases named in the same sentence as CLU in open-access papers (continued):
Sharing a sentence is not in itself a finding about the gene and the disease.
glioma (continued). "The combination of curcumin and CLU silencing may offer a novel therapeutic approach in gliomas, harnessing the apoptosis-promoting and survival-inhibiting effects of both treatments." (PMID 40573993, 2025). "In addition, the study identified CLU and BCL2L1 as key players in glioma progression, but the detailed molecular mechanisms underlying their interactions remain to be fully elucidated." (PMID 40606578, 2025). "However, the specific regulatory mechanisms of CLU in the context of glioma are not fully understood." (PMID 40606578, 2025). "All these findings emphasized the close involvement of CLU in immune status of gliomas." (PMID 37686218, 2023). "This study provided evidences that CLU was highly expressed in gliomas and might be an independent indicator to predict worse survival outcomes for LGG patients." (PMID 37686218, 2023). "Among 33 types of cancers, CLU showed highest expression in gliomas, including both GBM and LGG." (PMID 37686218, 2023). "We further investigated the expression distributions of CLU in gliomas." (PMID 37686218, 2023). "Further investigations focusing on the roles of CLU in gliomas are needed in future." (PMID 37686218, 2023). "We confirmed the close involvement of CLU in immune status of gliomas, which could be used as a biomarker or a specific target in glioma immunotherapy." (PMID 37686218, 2023). "However, the use of more diverse animal models, such as genetically engineered mice or patient-derived xenografts, could offer a more comprehensive understanding of CLU’s role in glioma progression." (PMID 40606578, 2025). "Downregulation of CLU has been shown to induce cellular senescence and inhibit cell proliferation in cancer cells, suggesting that targeting CLU could be a potential therapeutic strategy for gliomas." (PMID 40606578, 2025). "Results from our analyses indicated that high CLU expression positively correlated with the infiltrating abundance of different immune cells, such as macrophages, DCs, and CD4+ T cells, which suggest that CLU might modulate the recruitment of immune cells in TME of gliomas to some extent." (PMID 37686218, 2023). "However, the specific functions of CLU in gliomas have been scarcely explored." (PMID 37686218, 2023). "Thus, we speculated that CLU might have the potential to be a biomarker or a specific target in glioma immunotherapy." (PMID 37686218, 2023). "However, expression and the specific roles of CLU in glioma are rarely investigated." (PMID 37686218, 2023). "The current study’s findings are based on experiments conducted in nude mice, which provided valuable insights into the role of CLU and BCL2L1 in glioma progression." (PMID 40606578, 2025). "Bioinformatics analysis using TIMER2.0 and GEPIA 2.0 revealed positive correlations between CLU expression and several genes (BAX, BCL2L1, PRNP, HSPA5, LRP2, TTR, all p < 0.05), suggesting synergistic or antagonistic interactions during glioma development." (PMID 40606578, 2025). "Additionally, the involvement of CLU in the regulation of pro-inflammatory cytokines and the senescent phenotype indicates that it may play a role in the tumor microenvironment and contribute to the aggressiveness of gliomas." (PMID 40606578, 2025). "In vitro experiments using glioma cell lines (U251, SW1783, U87) demonstrated that CLU overexpression enhances cell migration and proliferation, while CLU knockdown inhibits these processes." (PMID 40606578, 2025). "GCL_TI specifically upregulates RG markers TNC, HOPX, PTPRZ1, and VIM, astrocyte markers CLU, LGALS1, as well as genes involved in migration and glioma network formation such as CD44, SPARC, and GAP43 (One peak)." (PMID 36823172, 2023). "We have also validated tumor markers such as CLU and CST3 for Meningioma, ANXA1 and SOD2 in Glioma and MAP2 for Medulloblastoma." (PMID 34055594, 2021).
glioma (continued). "In malignant glioma cells, OLIG2/DLL3 and AQP4/CLU distinguish tumor cells exhibiting transcriptomic features of oligodendrocytes and astrocytes, respectively." (PMID 34692159, 2020). "The findings above established a connection between CLU and BCL2L1, but whether CLU promotes glioma via BCL2L1 remained unclear." (PMID 40606578, 2025). "Functional assays revealed that CLU and BCL2L1 promoted glioma cell migration and proliferation." (PMID 40606578, 2025). "The complex interplay between CLU, BCL2L1, and other signaling pathways may vary across different glioma subtypes and genetic backgrounds." (PMID 40606578, 2025). "EGFR, BCAN, SOX2, PTN and CCN3 were found to be highly elevated in the glioma tumorous tissue with prominent fold change value, while other DE-ARGs, such as CLU, SCG3, showed no distinct expression alteration." (PMID 39033204, 2024). "Furthermore, both in vitro and in vivo experiments confirm that CLU’s pro-tumorigenic effects are mediated by BCL2L1, suggesting that targeting this pathway could be a promising therapeutic strategy for glioma treatment." (PMID 40606578, 2025). "In addition to these well-established glioma markers, we identified several other proteins that have never been associated with glioma biology including (e.g., SLC1A3, CLU, LGALS3BP, ANGPTL2, CRYAB and ITGB8)." (PMID 25360666, 2014).
rheumatoid arthritis (12 papers, 2014 to 2024). A chronic, systemic autoimmune disorder characterized by inflammation in the synovial membranes and articular surfaces. "In summary, we found increased serum concentrations of clusterin in treatment-naïve patients with early rheumatoid arthritis, and we suggest clusterin as a predictive biomarker of disease activity and treatment response." (PMID 34075162, 2021). "Conversely, decreased clusterin has been observed in rheumatoid arthritis synovial tissues." (PMID 25287745, 2014). "There was profound increment of interleukin 4 (IL-4), IL-5, and clusterin (P < 0.001) in the salivary proteome of 48 patients with pSS, compared to controls without pSS including 12 patients with rheumatoid arthritis (RA) and 12 healthy individuals." (PMID 26362815, 2015). "Similarly, CLU was highly expressed in the synovia of patients with rheumatoid arthritis." (PMID 24803721, 2014). "CLU mRNA expression in synovial tissue is decreased in rheumatoid arthritis (RA) compared with its expression in OA or healthy tissue, but the protein levels in synovial fluid are equally present in RA and OA." (PMID 30053814, 2018).
glaucoma (11 papers, 2009 to 2023). Increased pressure in the eyeball due to obstruction of the outflow of aqueous humor. "Supporting these findings, two membrane attack complex (MAC) assembly endogenous inhibitors, vitronectin and clusterin, were also found to be upregulated in glaucoma." (PMID 28978942, 2017). "Clusterin functions as a chaperone and was described to be neuroprotective in the context of glaucoma in the interplay between interleukin-6 (IL-6), vascular endothelial growth factor (VEGF), and hypoxia-1α." (PMID 29135941, 2017). "In PXS eyes, a significant down regulation of clusterin mRNA was seen in all anterior segment tissues, irrespective of the presence of glaucoma, when compared to normal eyes and eyes with primary open-angle glaucoma." (PMID 23157966, 2012). "As clusterin is a multifunctional protein, its expression has also been reported to increase markedly in response to many other types of cellular stress, including oxidative stress, an important factor involved in glaucoma pathogenesis." (PMID 33422048, 2021). "On the DI network for glaucoma, clusterin is connected to two major hubs, AP-1 and NF-κB." (PMID 19426536, 2009). "GAS7 may interact with other genes implicated in glaucoma pathogenesis such as MYOC, OPTN, WDR36, CAV1, nitric oxide synthase 2 (NOS2), forkhead box C1 (FOXC1), apolipoprotein E (APOE), amyloid precursor protein (APP), and clusterin (CLU)." (PMID 32545285, 2020). "Consistent with mass spectrometry findings, we observed that A2M, B2M, Clusterin, TNC, FVII, Adiponectin, CRP, SAA, ICAM-1 and VCAM-1 were differentially affected in the retinas and vitreous of glaucoma subjects." (PMID 28978942, 2017). "However, eight proteins (C6, C8G, CFH, C3, CFHR1, CFI, CLU, and SERPING1) were significantly downregulated in Caucasian glaucoma subjects." (PMID 37763167, 2023). "Based on these findings, clusterin may be important not only in PEX, but also in all glaucoma types." (PMID 33422048, 2021). "Our immunohistochemistry and shotgun proteomics data fully supported the transcriptomic data, showing accumulation of clusterin, complement factors H and B, and complement protein C3c, a by-product of activation of the key complement protein C3 in ONH of eyes with glaucoma." (PMID 19426536, 2009).
ischemia (11 papers, 2008 to 2025). A hypoperfusion of the BLOOD through an organ or tissue caused by a PATHOLOGIC CONSTRICTION or obstruction of its BLOOD VESSELS, or an absence of BLOOD CIRCULATION. "Of these, various proteins have been previously linked to ischemia, including clusterin, vimentin, and vitronectin." (PMID 37175625, 2023). "Clusterin, also known as apolipoprotein J, is expressed from a variety of tissues and implicated in pathological disorders such as neurodegenerative diseases, ischemia and cancer." (PMID 24073260, 2013). "Clusterin is a heat shock protein-like intra- and extracellular chaperone and its expression is stimulated by cellular stress and tissue injury (e.g., ischemia, inflammation, apoptosis, oxidative stress, heat stress and ionising radiation)." (PMID 32605184, 2020). "In the present study, we demonstrate using a cell culture model system that clusterin is partially responsible for increased cell tolerance of MSCGATA-4 to ischemia." (PMID 26962868, 2016). "However, on the other hand, clusterin was observed to be neuroprotective in focal cerebral ischemia, as evidenced by thinner size of the penumbra, less apoptotic cells at day 7 after ischemia, and improved remodeling in late ischemic phase." (PMID 34897996, 2022). "However, the role of clusterin in ischemia is controversial because several studies demonstrate that clusterin suppresses recovery from brain injury." (PMID 32084011, 2020). "Excessive accumulation of clusterin in glial cells, however, correlated with neurotoxicity in brain ischemia; it promoted microglia activation and to contributed to RGC loss in a retinal hypoxia-ischemia model." (PMID 19426536, 2009). "Interestingly, clusterin, lipocalin 2, litaf, and TNFR1a are also upregulated by other injuries as elevation of intraocular pressure (IOP) or ischemia." (PMID 18552980, 2008).
kidney damage (11 papers, 2014 to 2025). "In contrast, the positive correlation between clusterin and urinary protein levels at 3 months (T3) (r = 0.599, p = 0.031) highlights the potential role of clusterin as a marker of ongoing kidney damage." (PMID 40428765, 2025). "Even after the initial phase of treatment, fibrotic processes remain central to the ongoing kidney damage, with elevated levels of CLU indicating that fibrosis contributes to the persistence of kidney injury." (PMID 40428765, 2025). "A preliminary evaluation of some biomarkers of kidney damage (clusterin, cystatin B, inosine and NGAL) has been reported previously." (PMID 36196592, 2022). "Significantly increased systemic kidney injury biomarkers KIM-1, NGAL, and clusterin confirmed the presence of diabetic nephropathy and kidney damage in 20-week-old obese ZSF1 male rats." (PMID 32804947, 2020). "Upregulation of clusterin/apolipoprotein J has been reported in nephropathy models, suggesting it has a protective role in nephropathogenesis." (PMID 25148511, 2014). "Interestingly, our results found that workers at cold rolling had a high susceptibility to kidney damage due to their defect in DNA repair gene expression, whereas both kidney damage biomarkers KIM-1 and clusterin were higher in workers from cold rolling than oven areas." (PMID 36418822, 2023). "The study evaluated 914 adolescents aged 11–18 through urine samples to assess the presence of kidney damage biomarkers (OPN, KIM-1, CLU, NGAL, and Cys-C) by using Luminex Magpix and trace metals (Cd, Hg, Cu, Zn) by using ICP-mass." (PMID 40869301, 2025). "The renal epithelial biomarkers Calbindin, Clusterin, KIM-1, Osteoactivin (OA), and VEGF are known to indicate kidney damage and display elevated levels in urine across various kidney disorders." (PMID 38231282, 2024). "Urine markers of kidney damage were improved, as evidenced by lower urinary levels of NGAL, clusterin, and albumin." (PMID 37047807, 2023). "Our animal model of renal IRI produced elevated oxidative stress (inactivation of GST, increased GSSG levels, and elevated lipid peroxidation), decreased the glomerular filtration rate, and increased kidney damage (NGAL and clusterin)." (PMID 34829595, 2021).
Sepsis (11 papers, 2011 to 2026). Sepsis is defined as life-threatening organ dysfunction caused by a dysregulated host response to infection. "This study highlights significantly elevated clusterin levels in critically ill patients, predominantly in non-sepsis conditions, and associates circulating clusterin to inflammatory and metabolic dysfunctions." (PMID 36553017, 2022). "In the Severe vs. Control group, the genes associated with ER stress, including CLU (p = 0.01), BCL2L1 (p = 0.015), USP14 (p = 0.046), BFAR (p = 0.004), and OPA1 (p = 0.012), demonstrated a significant positive correlation with sepsis score." (PMID 40867920, 2025). "In our recently published paper, we showed that clusterin binds to circulating histones and neutralises their inflammatory, thrombotic and cytotoxic properties both in vitro and in vivo (experimental sepsis)." (PMID 40418078, 2025). "Further analysis of the correlation between sepsis feature genes and immune cells revealed that CLU, GLPX, and CKAP4 were negatively correlated with CD4 naive T cells, while DPEP2 and BCL11B were positively correlated." (PMID 41359645, 2025). "In line with these previous findings, ICU patients with sepsis showed significantly lower clusterin levels than non-sepsis patients in our study." (PMID 36553017, 2022). "During febrile neutropenia in patients with haematological malignancies, pentraxin 3 (PTX3), a soluble innate immunity receptor, increases with severe sepsis, while clusterin, a chaperon protein involved in extracellular histones clearance, decreases in patients with quick SOFA score (qSOFA) ≥2." (PMID 40722110, 2025). "We prospectively studied pentraxin 3 (PTX3), a soluble innate immunity receptor, and clusterin (CLU), a chaperone protein that binds extracellular histones during sepsis, in patients experiencing febrile neutropenia after intensive treatment for haematological malignancies." (PMID 40722110, 2025). "Under high λ conditions, we observed that the genes GLPX, CKAP4, CXCR4, and CLU maintained significant positive values, suggesting that these four genes may be key predictors of sepsis." (PMID 41359645, 2025). "The plasma concentration of CLU was significantly higher in critically ill patients compared to healthy individuals, which aligns with the current study that demonstrates increased CLU expression, albeit at the transcriptional level, in foals suffering from sepsis." (PMID 40867920, 2025). "Notably, Garcia-Obregon and colleagues found lowered clusterin concentrations in patients with sepsis." (PMID 36553017, 2022). "Moreover, for the first time, we were able to demonstrate that ICU patients in general (sepsis and non-sepsis) showed a significant increase of clusterin." (PMID 36553017, 2022). "In these patients, receiver operating curve (ROC) analysis showed a lower diagnostic sensitivity and specificity of clusterin for the detection of sepsis compared with interleukin-6 and procalcitonin (data not shown)." (PMID 36553017, 2022). "The levels of CLU, BCL2L1, USP14, PTPN1, OPA1, and CREB3 were elevated during sepsis and demonstrated a positive correlation with sepsis score." (PMID 40867920, 2025). "This study presents findings on several genes linked to ER stress, including CLU, BCL2L1, USP14, BFAR, and OPA1, which showed a positive correlation with sepsis score and a negative correlation with the combined activities of antioxidant enzymes." (PMID 40867920, 2025). "Ultimately, by taking the intersection of the results from the three machine learning methods, we identified six feature genes in sepsis: CD81, CLU, GLRX, CKAP4, DPEP2, and BCL11B; and seven feature genes in atrial fibrillation: LDHB, CD81, PFKFB2, CKAP4, CXCR4, DPEP2, and RORA." (PMID 41359645, 2025). "We analyzed clusterin plasma concentrations in 200 critically ill patients (133 with sepsis, 67 without sepsis) on admission to the medical intensive care unit (ICU)." (PMID 36553017, 2022).
Sepsis (continued). "In particular, plasma clusterin concentrations were significantly lower in patients with sepsis (n = 133, median 48.9 μg/mL, range 4.8–144.1 μg/mL) compared with patients without sepsis (n = 67, median 60.0 μg/mL, range 17.7–112.9 μg/mL)." (PMID 36553017, 2022). "The aim of this study was to determine the value of clusterin as a clinical biomarker in critical ill patients with or without sepsis." (PMID 36553017, 2022). "Moreover, we confirm decreased clusterin plasma concentrations in ICU patients with sepsis versus non-septic critically ill patients." (PMID 36553017, 2022). "Clusterin levels were significantly higher in non-septic ICU patients than in patients with sepsis." (PMID 36553017, 2022). "For this reason, we conducted a detailed investigation on the clinical relevance of clusterin in a meticulously documented cohort of ICU patients with and without sepsis." (PMID 36553017, 2022).
Stroke (11 papers, 2016 to 2024). Sudden impairment of blood flow to a part of the brain due to occlusion or rupture of an artery to the brain. "Serpina3n is upregulated in astrocytes and neurons within the ischemic penumbra after stroke and reduces brain damage possibly by interacting with clusterin and inhibiting neuronal apoptosis and neuroinflammation." (PMID 38253182, 2024). "SerpinA3N is expressed in astrocytes and penumbral neurons after stroke in mice and reduces damage possibly via interacting with clusterin and inhibiting neuronal apoptosis." (PMID 34897996, 2022). "In CNS, clusterin mRNA is detected in neurons and glia, and its expression is upregulated in astrocytes in a variety of disease states including AD, stroke, and seizure." (PMID 34897996, 2022). "Our study showed distinct clusterin immunoreactivity in cerebral blood vessels in subjects with different microvascular disorders, including familial early‐onset stroke disorders." (PMID 25940137, 2016). "Fluid phase identification of inactive pre-MAC complexes with protein S such as sC5b-7, 8 and 9 in addition to VTN and CLU may also provide further information on the regulatory activity of the MAC in stroke survivors." (PMID 32849183, 2020). "Longitudinal post-stroke blood proteomics profiles suggest that the alternative pathway of complement activation remains in a state of higher activation from 3-7 days to 3 months post-stroke, while simultaneously being regulated by clusterin and vitronectin." (PMID 32849183, 2020). "LAMA2, MLL4 and PLXDC2 are specifically expressed in (pre-)diabetic sera; CD99 is expressed in the sera of both healthy and (pre-)diabetic patients; and CD14, CLU and SAA2 are expressed in the sera of healthy, (pre-)diabetic and stroke subjects." (PMID 33995275, 2021). "Our previous studies on sTLR 2 and 4, sRAGE and Clusterin in CSF of SAH patients were limited by the methodology, i.e. ELISA assays of proteins preselected as a result of a thorough review of the stroke and neuroinflammatory disease literature." (PMID 31637049, 2019). "However, we found that CD14, CLU and SAA2 were expressed in the sera of stroke patients at various levels." (PMID 33995275, 2021).